PTH (parathyroid hormone)
Diseases named in the same sentence as PTH in open-access papers (continued):
Sharing a sentence is not in itself a finding about the gene and the disease.
Hypercalcemia (continued). "Being a rare event, malignant hypercalcemia from intact PTH ectopic production should be considered in these patients." (PMID 36909108, 2023). "On admission, he was found to have an elevated albumin-corrected serum calcium of 13.6 mg/dL, a serum phosphorus of 2.2 mg/dL and an intact PTH of 6 pg/mL (normal 18–90) with a PTHrP of 8.1 pmol/L (normal < 4.3), consistent with PTHrP-dependent hypercalcemia." (PMID 37328745, 2023). "The patient’s hypercalcemia was resolved with decreasing levels of PTH observed after the operation." (PMID 37280629, 2023). "The APA group had moderate hypercalcemia (mean 3.02 ± 0.44mmol/L) with elevated serum PTH (median 593.0pg/ml) and proportion of hypercalcemic crisis as 22.8%, all higher than those of benign lesions but lower than those of PC group." (PMID 36777354, 2023). "The subject’s very high values of total calcium (16.71 mg/dL) and PTH (2151 pg/mL) required prompt intervention; 60 mg of denosumab was administered (in addition to standard care), and his hypercalcemia rapidly reduced within 12 h." (PMID 37893182, 2023). "A total of 23 patients were started on cinacalcet for the treatment of hypercalcemia (calcium > 10.3 mg/dl) and parathyroid hormone (PTH) elevation (>65 pg/ml)." (PMID 37069889, 2023). "Prediction of PTH was strongest in the setting of hypercalcemia, with James having the highest Spearman correlation coefficient (+0.496) similar to including all parameters (+0.499)." (PMID 37251673, 2023). "In the acute setting, PTH-independent hypercalcemia is typically treated with anti-resorptive agents such as zoledronic acid or denosumab." (PMID 37328745, 2023). "The diagnosis of primary hyperparathyroidism was based on the presence of hypercalcemia with either concomitant elevated PTH levels (4/12) or inappropriately normal, unsuppressed PTH values i.e., a PTH >3.5-6.9mmol/L (8/17)." (PMID 37293490, 2023). "Case 1 presented initially with PTH-dependent hypercalcemia, with localization of a left upper parathyroid adenoma on parathyroid technetium sestamibi (99mTc-MIBI) uptake study." (PMID 37701149, 2023). "THPT is a condition characterized by the persistent release of PTH and loss of feedback regulation to blood calcium levels, resulting in hypercalcemia and elevated PTH levels, originally described in 1970s." (PMID 37854190, 2023). "Previous studies have documented that PHPT is characterized by hypercalcemia and elevated or abnormal PTH levels." (PMID 38152136, 2023). "We find that adjustment of TCa for albumin does not outperform unadjusted values in the prediction of Ca2+ in an unrestricted dataset and that the relationship between PTH and calcium is strongest in the setting of hypercalcaemia." (PMID 37251673, 2023). "Primary hyperparathyroidism (PHPT) is a disorder in which one or more parathyroid glands overproduce parathyroid hormone, leading to hypercalcemia." (PMID 36843806, 2023). "Laboratory results were also remarkable for leukopenia, microcytic anemia, hyperkalemia, anion gap metabolic acidosis, and non-PTH dependent hypercalcemia." (PMID 38152816, 2023). "Global- and kidney-specific Sik2/Sik3 mutant mice showed Cyp27b1 upregulation, elevated serum 1,25-vitamin D, and PTH-independent hypercalcemia." (PMID 36862513, 2023). "Investigations revealed left-sided lung consolidation, acute renal failure, and severe non–parathyroid hormone (PTH)–mediated hypercalcemia (calcium, 3.55mol/L; PTH, 0.81pmol/L)." (PMID 37274338, 2023). "In the setting of elevated extracellular calcium (hypercalcemia), the release of PTH is inhibited; conversely, low extracellular calcium (hypocalcemia) leads to the release of PTH." (PMID 37790033, 2023). "Upon discovering elevated PTH and hypercalcemia, the management strategy had to be revised to target the PHPT." (PMID 39239219, 2023).
Hypercalcemia (continued). "From the suspicion of PHPT as a result of the hypercalcemia and the pathological fractures, measurements for PTH levels were performed, resulting in 3000 pg/mL (normal range is 10–55 pg/mL)." (PMID 37653552, 2023). "In contrast, calcimimetics such as cinacalcet and etelcalcetide are typically used to treat PTH-dependent hypercalcemia (e.g., primary and tertiary hyperparathyroidism) or to reduce PTH in secondary hyperparathyroidism." (PMID 37328745, 2023). "The most common TRAEs in the TransCon PTH group were injection‐site reactions (19/61, 31.1%), hypercalcemia (6/61, 9.8%), and headache (6/61, 9.8%)." (PMID 36271471, 2023). "Laboratory results revealed elevated parathyroid hormone levels and hypercalcemia, leading to a diagnosis of hyperparathyroidism." (PMID 39239219, 2023). "The elevation of osteoclastic bone resorption, renal calcium tubules, intestinal calcium intake (through increased production of calcium-binding protein in enterocytes), and decreased PTH synthesis are the regular mechanisms of hypercalcemia." (PMID 37505607, 2023). "High-normal PTH levels in the setting of hypercalcemia suggest the presence of PTH-mediated hypercalcemia or parathyroid carcinoma." (PMID 37033238, 2023). "The patient was diagnosed with PTH-independent hypercalcemia secondary to foreign body reaction in areas of oil injection." (PMID 37011375, 2023). "Similar to Six2-Cre;Sik1fl/+;Sik2fl/fl;Sik3fl/fl mice, only Six2-Cre;Sik2fl/fl;Sik3fl/fl mice showed increased Cyp27b1 expression and serum 1,25-vitamin D levels, mild (but statistically significant) hypercalcemia, and PTH suppression." (PMID 36862513, 2023). "The persistent inappropriate elevation of 1,25(OH)2D levels as indicated by the elevated 1,25(OH)2D/PTH ratio in both types likely accounts for the mild ongoing hypercalcemia and intermittent hypercalciuria." (PMID 36990163, 2023). "Although rare, hypercalcemia induced by ectopic tumoral secretion of PTH can be an additional mechanism." (PMID 36909108, 2023). "Severe PTH-independent hypercalcemia is most commonly secondary to hypercalcemia of malignancy, and this was consistent with his history of weight loss." (PMID 37274338, 2023). "After taking a detailed history, and obtaining serum calcium levels, PTH and Vitamin D levels should be estimated to classify the type of hypercalcemia: PTH Dependent or PTH Independent." (PMID 37900460, 2023). "The median PTH, mean eLBR, median dLBR, median dLTR, and median PTH/Svol values were lower in mild hypercalcemia group compared to marked hypercalcemia group, while the median phosphorus levels were higher." (PMID 37892003, 2023). "Upon further assessment, she was noted to demonstrate hypercalcemia (10.24 mg/dL), suppressed PTH, significant osteoporosis, and elevated alkaline phosphatase; the presentation is presumed to be due to PTHrP." (PMID 37790033, 2023). "There was a numerically greater incidence of hypercalcemia with TransCon PTH within the first 3 months of treatment and a consistently greater incidence of hypocalcemia with placebo throughout the trial." (PMID 36271471, 2023). "Accurate localization of parathyroid adenomas is paramount in hypercalcemia and elevated parathyroid hormone (PTH) levels." (PMID 38106699, 2023). "Laboratory tests confirmed hypercalcemia of 12.62 mg/L, low levels of PTH (10 pg/mL), hyperphosphatemia (6.0 mg/dL), 25(OH)D of 23.3 ng/mL, and elevated 1,25(OH)2D (138 pg/mL)." (PMID 37011375, 2023). "Case Presentation: A 49-year-old lady presenting with generalised myalgia was found to have a parathyroid-dependent severe hypercalcaemia, (adjusted calcium 3.93mmol/L, PTH of 134pmol/L)." (PMID 37434225, 2023). "Mild hypercalcemia in patients with acromegaly is common and primarily parathyroid hormone-dependent which occurs as a result of concurrent parathyroid hyperplasia in patients with MEN-1." (PMID 36841880, 2023).
Hypercalcemia (continued). "The first case depicts a 34-year-old female, presenting with hypercalcemia towards the end of gestation (11.9-14.0 mg/dL at weeks 35 and 38), alongside suppressed PTH and elevated PTHrP." (PMID 37790033, 2023). "PHPT is the result of an autonomous PTH oversecretion from abnormal PG(s) determining hypercalcemia, hypophosphatemia, and elevated urinary calcium, with potential complications on the skeletal, renal, neurocognitive, and cardiovascular systems." (PMID 37048571, 2023). "We excluded from the search the studies focused on non-PTH related hypercalcemia, secondary, and/or renal/tertiary hyperparathyroidism, and vitamin D supplementation." (PMID 37509698, 2023). "The main clinical symptoms were high parathyroid hormone and hypercalcemia with bone injury and other complications." (PMID 38019325, 2023). "Laboratory analysis of whole blood and plasma identified severe total hypercalcemia, marked hypophosphatemia, markedly increased parathyroid hormone concentration, and marked lymphocytosis." (PMID 37118906, 2023). "Hypercalcemia suppresses the release of PTH and thus the production of 1,25-dihydroxyvitamin D. However, in some tumor types, 25-dihydroxyvitamin D is produced extrarenally from 25-hydroxyvitamin D, independent of PTH control." (PMID 37033238, 2023). "Primary hyperparathyroidism (PHPT) is a common endocrinopathy in clinical practice, characterized by hypercalcemia due to increased production of the parathyroid hormone (PTH) by one or more parathyroid glands." (PMID 36651703, 2023). "It is characterized by markedly elevated vitamin D concentrations (usually > 150 ng/ml), hypercalcemia, hypercalciuria and PTH suppression." (PMID 38129893, 2023). "According to the existing results in the literature, the suspicion of PC should be based on severe PTH high levels, hypercalcemia, bone and kidney diseases, and an evident neck mass." (PMID 38027123, 2023). "We present a case of post-surgical persistent hypercalcemia and elevated parathyroid hormone (PTH) levels in a 44-year-old woman with previously undetected parathyroid adenoma." (PMID 37415163, 2023). "The postulated mechanisms included correction of hypercalcemia, attenuation of vascular calcification and vascular stiffness and a direct effect of PTH on the vascular wall." (PMID 37484844, 2023). "Primary hyperparathyroidism (PHPT) and familial hypocalciuric hypercalcemia (FHH) are the main differential diagnoses in a patient presenting with parathyroid hormone (PTH)-mediated hypercalcemia." (PMID 38021951, 2023). "Despite parathyroidectomy (180 mg adenoma), hypercalcemia, hypercalciuria, and low normal PTH levels persisted." (PMID 37701149, 2023). "Idiopathic Infantile Hypercalcemia (IIH) is characterized by hypercalcemia and hypercalciuria owing to PTH-independent increases in circulating concentrations of 1,25(OH)2D." (PMID 36990163, 2023). "Parathyroid carcinoma (PC) is a rare malignant, usually hormonally active neoplasm which accounts for <1% of all the cases of primary hyperparathyroidism (PHPT) characterized by excessive secretion of parathyroid hormone (PTH) and hypercalcemia." (PMID 37183888, 2023). "His kidney function has fluctuated (Cr 0.9–3.1 mg/dL) over the preceding two years, with consistent hypercalcemia, hypercalciuria (637 mg/24 hours), and low PTH level." (PMID 37280532, 2023). "If this is the sole mechanism of action, calcimimetics would seem to have little role in the treatment of PTH-independent hypercalcemia in which the PTH is already suppressed." (PMID 37328745, 2023). "Differentiating between PTH-dependent and PTH-independent hypercalcemia is crucial in clinical practice." (PMID 37799241, 2023). "Primary hyperparathyroidism (PHPT) is an endocrine disorder characterized by hypercalcaemia and elevated or inappropriately normal concentrations of parathyroid hormone." (PMID 37364141, 2023).
Hypercalcemia (continued). "A 37-year-old Caucasian female with a history of gonadotropin-secreting pituitary microadenoma and recurrent nephrolithiasis was found to have hypercalcemia, hypercalciuria, elevated 1,25-dihydroxyvitamin D levels, and low parathyroid hormone levels." (PMID 37465813, 2023). "It is generally excluded if the parathyroid hormone (PTH) value is <20 pg/mL (termed PTH-independent hypercalcemia)." (PMID 37265703, 2023). "In normal situations, negative feedback of the parathyroid is an essential role to maintain the homeostasis of calcium absorption, but a very low concentration of PTH is a hypercalcemia symptom." (PMID 37505607, 2023). "The next step in the evaluation of a patient with malignancy-related hypercalcemia consists of measuring both PTH and PTHrP." (PMID 37033238, 2023). "We present a 51-year-old man who complained of nausea, vomiting, and significant weight loss during 1 month before his admission; the laboratory findings revealed severe hypercalcemia accompanied with low PTH." (PMID 37670372, 2023). "It is essential to consider parathyroid carcinoma in the differential diagnosis of PTH-dependent hypercalcemia as complete resection of the tumor at the initial operation is associated with optimal outcomes." (PMID 40729208, 2023). "Laboratory tests revealed elevated parathyroid hormone levels, hypercalcaemia, and hypophosphatemia." (PMID 36800629, 2023). "Hypercalcemia is a disordering homeostatic calcium disease with high levels of free 1,25(OH)2D in the blood and decreased expression of PTH." (PMID 37505607, 2023). "The pathogenesis of hypercalcemia in this disease begins with inappropriately elevated levels of a parathyroid hormone produced by the parathyroid gland." (PMID 36843787, 2023). "Primary hyperparathyroidism (PHPT) is an uncommon disorder characterised by hypercalcemia with an increased parathyroid hormone level." (PMID 37807045, 2023). "Acute hypocalcemia induces a selective, several-fold increase in bursts frequency and amplitude, whereas hypercalcemia suppresses the PTH pulsatile secretion component, as does prolonged calcitriol therapy." (PMID 36996072, 2023). "Primary hyperparathyroidism (PHPT) is the most common form of hyperparathyroidism (HPT), characterized by the excessive production of parathormone (PTH) by the parathyroid glands, and frequently leads to hypercalcemia." (PMID 37892003, 2023). "In those infants who develop hypercalcemia, determination of serum 1,25(OH)2D3 and parathyroid hormone (PTH) allows confirmation of PTH-independent hypercalcemia, while regular renal US monitoring is required to detect nephrocalcinosis." (PMID 37929024, 2023). "The second mechanism of paraneoplastic hypercalcemia is the ectopic PTH secretion by tumors, most of which are in the lung." (PMID 37670372, 2023). "All patients also demonstrated PTH-independent hypercalcaemia, with corrected calcium levels ranging between 2.69 to 3.30mmol/L and required admission for intravenous fluid rehydration." (PMID 37434225, 2023). "iTKO mice showed dramatic hypercalcemia with suppressed PTH levels, likely due to high 1,25-vitamin D levels and increased bone resorption." (PMID 36862513, 2023). "We describe a rare case of Graves' thyrotoxicosis presenting with severe cholestasis and non-parathyroid hormone-related hypercalcemia." (PMID 36960248, 2023). "It is likely that both intracellular hypercalcemia and hypophosphatemia alter the insulin receptor expression and response; the contribution of parathyroid hormone is less clear." (PMID 37350980, 2023). "Most of the patients had severe hyperparathyroidism (blood ionized calcium level > 1.13 mmol/L and PTH level > 60 pg/mL) and symptoms of hypercalcemia." (PMID 36013465, 2022). "During follow-up, one patient in the open group experienced hypercalcemia and PTH increase 10 months after operation, and was considered to be a case of recurrence." (PMID 36338640, 2022).
Hypercalcemia (continued). "Calcium oxalate was detected on urinalysis in addition to hypercalcemia, low phosphate, markedly elevated alkaline phosphatase and high parathyroid hormone (PTH) with a low 25 (OH) vitamin D3 level." (PMID 36529731, 2022). "While hypercalcemia due to malignancy is often brought about by PTH-related protein in adults, PTH-producing tumors are quite rare in clinical practice." (PMID 36544116, 2022). "An elevated or inappropriately normal serum PTH value in the presence of true hypercalcemia is always abnormal and typically indicates the presence of PHPT." (PMID 36408083, 2022). "After surgical therapy, the levels of PTH and calcium should be checked, and patients should be informed about the symptoms of hypercalcemia so they are aware of its occurrence." (PMID 36013465, 2022). "Treatment of uremic mice with the combination of 25(OH)D3 + paricalcitol resulted in PTH over-suppression, hypercalcemia and hyperphosphatemia, commonly occurring with excessive vitamin D therapy in advanced human CKD stages." (PMID 35807767, 2022). "PTH levels are often normal reflecting disturbance of hypercalcaemia-induced inhibition of PTH release." (PMID 36536367, 2022). "We report a case of a 57-year-old man with a known history of diabetes on empagliflozin for two years who presented with hypercalcemia and equivocal parathyroid hormone level." (PMID 35651422, 2022). "Twenty-four (60%) of 40 patients with normocalcemia and elevated PTH level and 56 (76%) of 74 patients with hypercalcemia (defined as iCa ≥ 1.3 mmol/L) combined with elevated PTH level had high -turnover bone disease." (PMID 34668028, 2022). "In T-PTX VDR +/+ and VDR−/− mice with constant PTH levels, hypercalcemia induced an increase in FGF23 levels, but to a lower extent in animals lacking VDR." (PMID 35807756, 2022). "In the typical patient with mild to moderate PHPT, plasma calcium and PTH levels can remain stable for years and when the hypercalcemia is mild (ie, less than 11.0 mg/dL [2.75 mmol/L]) patients often have relatively few symptoms." (PMID 36245271, 2022). "High parathyroid hormone levels and hypercalcemia induce 1,25(OH)2D3 synthesis, stimulating the transcription of CYP27B1 and increasing 1,25(OH)2D3 activity, with consequent down-stream action of CYP27B1 and suppression of parathyroid hormone." (PMID 35458148, 2022). "Primary hyperparathyroidism (PHPT) is the most common cause of hypercalcemia detected in outpatients and is characterized by hypercalcemia and high or inappropriately normal parathyroid hormone (PTH) levels." (PMID 36326370, 2022). "Primary hyperparathyroidism (PHPT) is defined as hypercalcemia with inappropriately elevated parathyroid hormone (PTH) levels for the hypercalcaemic state due to abnormal, incompletely regulated secretion of PTH from one or more of the four parathyroid glands." (PMID 36284286, 2022). "We present the preoperative detection of a giant parathyroid adenoma (GPA) using (99mTc)-sestamibi parathyroid scintigraphy in a patient presenting with severely elevated parathyroid hormone, hypercalcemia, hypophosphatemia, and vitamin D insufficiency." (PMID 36339511, 2022). "The proliferative parathyroid tissue autonomously secretes excessive parathyroid hormone (PTH), resulting in a series of clinical complications, such as hypercalcemia, urinary calculi, osteoporosis, bone fracture, and neuropsychiatric symptoms." (PMID 36010997, 2022). "It is characterized by overproduction of the parathyroid hormone (PTH) and hypercalcemia, leading to complications such as osteoporosis and formation of renal stones." (PMID 35586626, 2022). "Hypercalcemia in patients under ICI has also been reported but seems to be non-PTH-mediated in the context of humoral hypercalcemia of malignancy or PTH-related peptide production." (PMID 36149449, 2022). "Laboratory tests demonstrated severe hypercalcemia (Ca > 3.49 mmol/L), decreased parathyroid hormone (PTH), and vitamin D level." (PMID 35757138, 2022).